COL7A1 (collagen type VII alpha 1 chain)
Diseases named in the same sentence as COL7A1 in open-access papers (continued):
Sharing a sentence is not in itself a finding about the gene and the disease.
epidermolysis bullosa (53 papers, 2012 to 2026). Epidermolysis bullosa (EB) is a group of genetic skin diseases that cause the skin to blister very easily. "Two additional patients presenting with epidermolysis bullosa harbored truncating variants in COL7A1 (c.497dup; p.Val168Glyfs12) and EXPH5 (c.5786del; p.Pro1929Leufs8), respectively; the latter also carried a KRT5 missense variant (c.1607G>A; p.Ser536Asn)." (PMID 42194992, 2026). "An epidermolysis bullosa genetic panel identified a heterozygous pathogenic variant in COL7A1 (c.6007G > A, p.Gly2003Arg), confirming the diagnosis of dominant DEB." (PMID 41019009, 2025). "Although the causal association of COL7A1 to dystrophic epidermolysis bullosa is well established, its role in PPK requires further studies and validation." (PMID 39630431, 2025). "Dystrophic epidermolysis bullosa (DEB) patients have pathogenic variants in COL7A1, leading to skin fragility, blistering, and scarring." (PMID 40667654, 2025). "B-VEC, a replication-defective HSV-1 vector designed to restore functional C7 protein through the delivery of functional COL7A1, can treat wounds in patients 6 months or older with dystrophic epidermolysis bullosa caused by COL7A1 mutations." (PMID 39207577, 2024). "Our study reveals that Epidermolysis Bullosa patients with COL7A1 c.6163G > A and KRT14 c.377T>A variants have different clinical presentations, with dominant forms of Dystrophic EB having milder phenotypes than recessive ones." (PMID 38580989, 2024). "Many promising results have been published using the CRISPR/Cas9 technology to efficiently correct mutations in epidermolysis bullosa, especially for mutations in COL7A1, COL17A1, KRT5 and KRT14." (PMID 36901775, 2023). "RT-qPCR indicated that the mRNA level for Col7a1, of which mutation is known to cause hereditary epidermolysis bullosa, was elevated in the cystitis and was decreased by SB431542 treatment." (PMID 37931000, 2023). "The glycine–arginine substitution is also evident in dominant dystrophic epidermolysis bullosa, with the variant of COL7A1." (PMID 37189830, 2023). "For example, the delivery of the DNA template in an adeno-associated viral vector was found to increase the frequency of correction of a COL7A1 pathogenic variant by HDR by up to 50% in keratinocytes from individuals with epidermolysis bullosa." (PMID 35457228, 2022). "Mutations in the COL7A1 gene cause dystrophic epidermolysis bullosa, leading to subepidermal blistering and mucocutaneous fragility." (PMID 36175409, 2022). "In this regard, many scientists are determining the efficacy of certain drugs, ointments, and gene therapy in treating Epidermolysis bullosa, especially in COL7A1 mutation-affected patients." (PMID 35885431, 2022). "COL7A1 is typically known for its association with epidermolysis bullosa, a blistering skin condition caused by abnormal collagen organization." (PMID 33974636, 2021). "Dystrophic epidermolysis bullosa, featured with defective anchoring fibrils and consequent separation of the sub‐basal lamina, is caused by variants in the COL7A1 in either autosomal dominant or autosomal recessive fashion." (PMID 32537942, 2020). "Our study expands the mutation spectrum of COL7A1 and demonstrated that clinical exome sequencing and minigene assays were efficient tools for recessive dystrophic epidermolysis bullosa molecular diagnoses." (PMID 32537942, 2020). "The dystrophic forms of epidermolysis bullosa (EB) with mutations in COL7A1 or COL17A1 gene is one of the major forms of EB where patients present a fragile skin, which can shed at the slightest touch." (PMID 29738498, 2018). "Among the genes, we found COL7A1, a collagen gene linked to epidermolysis bullosa, a severe skin syndrome with elevated lifetime risk of melanoma." (PMID 28569218, 2017). "A nonsense mutation in the COL7A1 gene causes recessive epidermolysis bullosa in Vorderwald and Rotes Höhenvieh cattle." (PMID 27905875, 2016).
epidermolysis bullosa (continued). "In this study, we chose COL7A1 as a target gene, in which mutations lead to the severe dystrophic variant of the skin blistering disorder epidermolysis bullosa (DEB)." (PMID 27669223, 2016). "COL7A1 mutations are linked to two skin disorders, epidermolysis bullosa and keratosis palmoplantaris." (PMID 27955658, 2016). "Dystrophic epidermolysis bullosa is an inherited bullous dermatosis caused by the COL7A1 gene mutation in autosomal dominant or recessive mode." (PMID 23226319, 2012). "Germline mutations in COL7A1 could lead to dystrophic epidermolysis bullosa, resulting in an increased risk of squamous cell carcinoma." (PMID 40028167, 2025). "Besides, this therapeutic strategy can easily be adapted for mutations in other COL7A1 exons, other epidermolysis bullosa subtypes, and other genetic diseases." (PMID 38027067, 2023). "COL7A1 mutations lead to epidermolysis bullosa, and COL17A1 mutations cause bullous pemphigoid." (PMID 37800682, 2023). "Finally, they do not correspond with the patient’s medical and family history; for example, sequence changes of the COL7A1 or the TERT genes are associated with epidermolysis bullosa or dyskeratosis congenita, respectively." (PMID 35205015, 2022). "Dystrophic epidermolysis bullosa (DEB) is caused by mutations in the COL7A1 gene." (PMID 35163654, 2022). "Dystrophic epidermolysis bullosa is caused by mutations in the COL7A1 gene encoding collagen VII." (PMID 34650598, 2021). "There are 14 subtypes of dystrophic epidermolysis bullosa and 400 mutations of COL7A1." (PMID 31065125, 2018). "Sequence variants in COL7A1 cause epidermolysis bullosa in various species." (PMID 27905875, 2016). "Epidermolysis bullosa (EB), a genetic skin disorder commonly found in calves, buffalo lambs, and foals is caused by a missense mutation in the COL7A1 gene, which encodes type VII collagen." (PMID 39852942, 2025). "In epidermolysis bullosa (EB), more than 800 mutations in COL7A1 have been reported, leading to the dystrophic form of EB (DEB), a severe and rare skin blistering disease associated with a high risk of developing an aggressive form of squamous cell carcinoma." (PMID 36901775, 2023). "Dystrophic epidermolysis bullosa (EB) is a rare inherited blistering disease caused by mutations of the collagen type VII alpha 1 (COL7A1) gene." (PMID 37024925, 2023). "Significantly enriched keywords associated with our group of genes were Epidermolysis bullosa due to four genes with variants in our study group (EXPH5, PLEC, COL7A1, LAMB3)." (PMID 36454308, 2023). "Wang R., Sun L., Habulieti X., Liu J., Guo K., Yang X., Ma D.,Zhang X. Novel variants in LAMA3 and COL7A1 and recurrentvariant in KRT5 underlying epidermolysis bullosa in five Chinesefamilies." (PMID 36923479, 2023). "Mutations in COL7A1, which encodes type VII collagen, have been reported to cause dystrophic epidermolysis bullosa, an inherited epidermolysis bullosa that demonstrates activated autoimmunity and inflammatory responses." (PMID 37273692, 2023). "Our work suggests that testing for COL7A1 genetic variants should be considered in patients with EBA, which either have a patient history hinting towards underlying dystrophic epidermolysis bullosa or pose therapeutic challenges." (PMID 35464429, 2022). "TRIDs are, for example, shown to increase the expression of full-length COL7A1 in keratinocytes and fibroblasts in epidermolysis bullosa, but to our knowledge, TRIDs have not been tested in iPSC-derived neuronal models." (PMID 35237613, 2021). "Dystrophic epidermolysis bullosa is primarily caused by genetic loss of function or abundance of collagen VII, encoded by the COL7A1 gene, but a number of secondary, molecular and cellular, events modify the disease phenotype." (PMID 34650598, 2021). "Dystrophic epidermolysis bullosa is a type of epidermolysis bullosa caused by mutation in type VII collagen, COL7A1." (PMID 31065125, 2018).
epidermolysis bullosa (continued). "Dystrophic epidermolysis bullosa (DEB) is due to variation in the COL7A1 gene." (PMID 37556444, 2023). "Both COL17A1 and COL7A1 are involved in Epidermolysis Bullosa." (PMID 37414817, 2023). "For example, in the case of dystrophic epidermolysis bullosa, a neutral glycine substitution in the COL7A1 gene increased the effect of a dominant glycine substitution in the other copy of the COL7A1 gene, resulting to a more severe phenotype in the compound heterozygote." (PMID 29089023, 2017). "Epidermolysis bullosa (EB) is an inherited rare genetic skin disorder, and one of its most devastating subtypes is recessive dystrophic EB (RDEB), caused by biallelic mutations in the COL7A1 gene." (PMID 38027067, 2023). "Variants in COL7A1 and MTAP were not reported in ClinVar; however, variants in these genes are related to squamous cell carcinoma (as part of epidermolysis bullosa spectrum) and sarcoma." (PMID 32443704, 2020). "Previously, he was diagnosed with COL7A1:DEB, Bart-type non-specific epidermolysis bullosa through genetic testing." (PMID 35996499, 2022).
Dystrophic epidermolysis bullosa (38 papers, 2012 to 2025). "Pathogenic variants in the COL7A1 gene can lead to dystrophic epidermolysis bullosa (DEB), a severe skin disorder." (PMID 40790091, 2025). "Dystrophic epidermolysis bullosa (DEB) is a type of EB caused by mutations in the COL7A1 gene responsible for the production of type VII collagen." (PMID 40729225, 2025). "Pathogenic variants in COL7A1 are well-documented as the cause of dystrophic epidermolysis bullosa (DEB), with recessive inheritance typically associated with more severe clinical presentations, particularly in consanguineous populations." (PMID 40956805, 2025). "The proband is heterozygous for Dystrophic Epidermolysis Bullosa due to a COL7A1 allele with a glycine substitution at the triple helix domain." (PMID 38580989, 2024). "Prospect of ASO-based therapeutics for genodermatoses is also supported by a clinical trial (Phase I/II) of QR-313 for dystrophic epidermolysis bullosa due to mutations of the COL7A1 gene." (PMID 37364129, 2023). "Dystrophic epidermolysis bullosa (DEB) is caused by pathogenic variants in the COL7A1 gene encoding collagen VII." (PMID 37985760, 2023). "Dystrophic epidermolysis bullosa (DEB) is a genetic disorder marked by the mutation in COL7A1 gene and manifested by abnormal blistering of limb skin." (PMID 35337155, 2022). "Mutations within the COL7A1 gene underlie the inherited recessive subtype of the blistering skin disease dystrophic epidermolysis bullosa (RDEB)." (PMID 35163654, 2022). "Dystrophic epidermolysis bullosa (DEB) is an inheritable blistering disease caused by mutations in COL7A1, which encodes type VII collagen." (PMID 34948168, 2021). "COL7A1 variants have been identified in humans and dogs with dystrophic epidermolysis bullosa (DEB)." (PMID 33291836, 2020). "Dystrophic epidermolysis bullosa (DEB) is an inherited disease caused by mutations in COL7A1 that compromise expression of functional gene products." (PMID 33081018, 2020). "Mutations in COL7A1 cause dystrophic epidermolysis bullosa (DEB) (OMIM # 131750 # 226600) whereby the generally milder dominant DEB (DDEB) and non-syndromic congenital nail disorder-8 (OMIM # 607523) are due to missense mutations." (PMID 31387942, 2019). "Additionally, clinical conditions, namely dystrophic epidermolysis bullosa and epidermolysis bullosa acquisita, which involve COL7A1 mutations or autoantibodies, often manifest as alopecia and brittle hair." (PMID 40699867, 2025). "Moreover, at least 774 mutations within COL7A1 have been reported in different variants of dystrophic epidermolysis bullosa, which makes it necessary to develop customized gene editing therapies for each patient, which is time-consuming and expensive." (PMID 34884578, 2021). "(B)On the other hand, it would be expected that patients with disease such as dystrophic epidermolysis bullosa (DEB) which has symptoms derived from mutations in COL7A1 may also develop cancer." (PMID 31598831, 2019). "Dystrophic epidermolysis bullosa (DEB) is a rare inherited skin blistering disease stemming from mutations in COL7A1, the gene responsible for encoding the alpha-1 chain of type VII collagen (C7)." (PMID 40988071, 2025). "Dystrophic epidermolysis bullosa (DEB) is a rare blistering disorder caused by mutations in the COL7A1 gene encoding type VII collagen, a major component of anchoring fibrils." (PMID 39639148, 2025). "It has been shown that both forms of dystrophic epidermolysis bullosa (DEB) are caused by mutations in the COL7A1 gene." (PMID 39628969, 2024). "As an example, we focused on COL7A1 which is the mutational cause of Dystrophic Epidermolysis Bullosa (DEB) and had significant associations with patient outcomes in MSIH tumors." (PMID 35120467, 2022). "Here, we presented a 12-year-old boy carrying pathogenic COL7A1 mutation with diagnosis of dystrophic epidermolysis bullosa (DEB)." (PMID 35899130, 2022).
Dystrophic epidermolysis bullosa (continued). "Mutations in the gene coding for collagen VII (COL7A1) lead to a disease type known as dystrophic epidermolysis bullosa (DEB), which can be inherited in either a dominant (DDEB) or recessive (RDEB) manner." (PMID 34085701, 2021). "Dystrophic epidermolysis bullosa (DEB) is an intractable genetic blistering skin disease caused by mutations in COL7A1, which encodes type VII collagen." (PMID 34948168, 2021). "Dystrophic epidermolysis bullosa (DEB) is an inherited skin syndrome triggered by mutations to the kind VII collagen gene (COL7A1), located on chromosome 3, that deactivates a structural of protein synthesis and is a vital player for skin straightness." (PMID 34977000, 2021). "Mutations in the COL7A1 gene, which encodes collagen VII protein, have been identified as the primary cause of the disease recessive dystrophic epidermolysis bullosa." (PMID 41100460, 2025). "Mutations in gene COL7A1 are highly suggestive in DEB (Dystrophic Epidermolysis Bullosa)." (PMID 37623260, 2023). "Dystrophic epidermolysis bullosa (DEB) is an incurable and inherited skin disorder mainly caused by mutations in the gene encoding type VII collagen (COL7A1)." (PMID 36419915, 2022). "The COL7A1 gene encoding collagen type VII alpha 1 is located within this interval and COL7A1 mutations have been shown to cause inherited dystrophic epidermolysis bullosa (DEB) in humans." (PMID 22715415, 2012). "Mutations in COL7A1, which encodes collagen VII, led to recessive dystrophic epidermolysis bullosa." (PMID 41100460, 2025). "However, to date, only one Food and Drug Administration (FDA)-approved gene therapy is available for collagen disorders, which targets COL7A1 for the treatment of dystrophic epidermolysis bullosa." (PMID 40790091, 2025). "Available research concentrated on COL7A1 in all forms of dystrophic epidermolysis bullosa." (PMID 38111702, 2023). "Among these, mutations in COL7A1 and COL17A1 were associated with dystrophic epidermolysis bullosa." (PMID 34901026, 2021). "The COL7A1 gene is distinct from other collagen genes in that some glycine substitutions can be silent in the heterozygous state, while other glycine substitutions may manifest in the generally milder, dominantly inherited dystrophic epidermolysis bullosa." (PMID 33081018, 2020). "Several stop-gain variants in COL7A1 and COL17A1 are identified in our study; these disrupt protein structures critical to dermal-epidermal cohesion, leading to severe dystrophic epidermolysis bullosa (DEB) phenotypes." (PMID 40956805, 2025).
gastric cancer (9 papers, 2019 to 2025). A primary or metastatic malignant neoplasm involving the stomach. "In a recent study, upregulated COL7A1 expression was suggested to have prognostic significance and cause distant metastasis in gastric cancer." (PMID 36010952, 2022). "Studies focused on COL7A1 demonstrated that COL7A1 is significantly upregulated in gastric cancer tissues and is an independent risk factor for poor prognosis in gastric cancer." (PMID 36159988, 2022). "Third, we further investigated the association between the clinicopathologic variables of gastric cancer patients and COL7A1 expression and evaluated the prognostic significance of COL7A1 expression levels." (PMID 34512204, 2021). "To our knowledge, we are the first to reveal the association between COL7A1 expression and gastric cancer through immunohistochemistry and to confirm its prognostic significance." (PMID 34512204, 2021). "As an important component of the tumor microenvironment, COL7A1 demonstrated prognostic value in patients with gastric cancer and pancreatic cancer." (PMID 38111702, 2023). "The expression of COL7A1 showed a significant prognostic value for OS and distant metastasis in gastric cancer." (PMID 35993054, 2022). "In this study, we also began with a DNA microarray to explore the expression of various genes in gastric cancer and found that two types of collagen were highly expressed in cancer tissues: COL7A1 and COL1A1." (PMID 34512204, 2021). "The site and total immunohistochemistry score of COL7A1 expression in gastric cancer showed prognostic significance for OS and distant metastasis, respectively." (PMID 34512204, 2021). "In conclusion, we have shown that COL7A1 is overexpressed in gastric cancer and confirmed the clinical and prognostic significance of the intracellular expression of COL7A1." (PMID 34512204, 2021). "Using microarray technology, a previous gene expression analysis in gastric cancer found that the expression of several collagen genes increased in gastric cancer tissue, and COL7A1 was one of them (Cancer 119.1, Normal 46.7, Cancer/Normal 2.6, p < 0.05)." (PMID 34512204, 2021). "Our aim in this study was to reveal the clinical significance and prognostic effects of a newly found upregulation of COL7A1 expression in gastric cancer patients." (PMID 34512204, 2021). "First, we explored many genes differentially expressed in gastric cancer tissue, including COL7A1, with a DNA microarray." (PMID 34512204, 2021). "This study reveals a novel biomarker candidate, type VII collagen (COL7A1), in patients with gastric cancer." (PMID 34512204, 2021). "Second, we performed immunohistochemistry to evaluate the levels of COL7A1 expressed in gastric cancer tissue and adjacent normal tissue." (PMID 34512204, 2021). "The mean of total immunohistochemistry score of COL7A1 was higher in gastric cancer tissue than in normal stomach tissue (7.50 versus 6.93, p = 0.001)." (PMID 34512204, 2021). "In the microarray, COL7A1 was upregulated in gastric cancer tissue compared with normal tissue." (PMID 34512204, 2021). "To perform immunohistochemistry and validate the upregulation of COL7A1 expression, we collected 200 more gastric cancer tissues and 100 normal gastric tissues from 200 randomly selected patients who underwent gastrectomy for gastric cancer between January 2010 and December 2013." (PMID 34512204, 2021). "The clinicopathological significance of unregulated COL7A1 expression in gastric cancer has not yet been studied." (PMID 34512204, 2021).